RNU6-1062P (RNA, U6 small nuclear 1062, pseudogene)
Gene: Small nuclear RNA gene on chromosome 1 (151,629,324 to 151,629,430, forward strand). Ensembl gene ENSG00000206635.
Homologues: Orthologues: chimpanzee U6 (99% identical), macaque U6 (91% identical), rabbit U6 (81% identical), rat U6 (77% identical). Paralogues in human: RNU6-12P (87% identical), RNU6-13P (87% identical), RNU6-16P (87% identical), RNU6-32P (87% identical), RNU6-33P (87% identical), RNU6-49P (87% identical), RNU6-1 (86% identical), RNU6-1124P (86% identical), RNU6-11P (86% identical), RNU6-17P (86% identical), RNU6-18P (86% identical), RNU6-2 (86% identical), and 1286 more.